PCSK9 (proprotein convertase subtilisin/kexin type 9)
Diseases named in the same sentence as PCSK9 in open-access papers (continued):
Sharing a sentence is not in itself a finding about the gene and the disease.
anemia (2 papers, 2020 to 2022). A reduction in the number of red blood cells, the amount of hemoglobin, and/or the volume of packed red blood cells. "In a previous study, SCD mice with deficiency of proprotein convertase subtilisin/kexin type 9 (PCSK9) were observed to have more severe anemia and increased sickling compared to control SCD mice." (PMID 36180774, 2022). "The worsened anemia due to PCSK9 deficiency was associated with increased iron staining in liver, spleen, and kidney sections." (PMID 33020528, 2020). "In conclusion, deficiency of PCSK9 is associated with worsened anemia in SCD mice due to increased hemolysis." (PMID 33020528, 2020). "Although cholesterol levels were lower in Pcsk9−/−, SCDbmt mice compared to Pcsk9+/+, SCDbmt mice, anemia was more severe in Pcsk9−/−, SCDbmt mice." (PMID 33020528, 2020). "Reticulocyte percentages were higher in PCSK9 deficient mice suggesting anemia was not due to impaired erythropoiesis but rather increased hemolysis." (PMID 33020528, 2020). "However, our finding of increased reticulocytosis with worsened anemia in Pcsk9−/−, SCDbmt mice compared to Pcsk9+/+, SCDbmt mice suggests that increased hemolysis was contributing to more severe anemia." (PMID 33020528, 2020). "While we hypothesized that erythrocyte turnover might be reduced through beneficial vascular effects of lipid lowering, we found more severe anemia in mice lacking PCSK9." (PMID 33020528, 2020). "Although PCSK9 affects circulating low density lipoprotein (LDL) by regulation of the LDL receptor, the effect of PCSK9 on anemia was independent of LDL receptor expression." (PMID 36180774, 2022). "Anemia was evident in all mice receiving bone marrow from an SCD donor, however, anemia was more severe in mice lacking PCSK9." (PMID 33020528, 2020).
Anxiety (2 papers, 2022 to 2024). Intense feelings of nervousness, tension, or panic often arise in response to interpersonal stresses. "To investigate the impact of PCSK9 deficiency on brain function, we studied PCSK9-deficient mice and WT controls in a battery of behavioral tests assessing spatial-and motor learning as well as anxiety-related behavior." (PMID 36733269, 2022).
aortic aneurysm (2 papers, 2021 to 2026). A ruptured aneurysm located in the wall of the proximal portion of the descending aorta proceeding from the arch of the aorta. "We found that genetically proxied PCSK9 could decrease the risk of aortic aneurysms in the UK Biobank cohort (OR = 0.63, 95% CI = 0.46–0.85, p = 3.2 × 10−3); however, this was not replicated in the FinnGen cohort (OR = 0.87, 95% CI = 0.69–1.10, p = 0.24)." (PMID 34834523, 2021). "Apart from HMGCR and PCSK9 inhibitions, ANGPTL3 might be another potential target for the treatment of aortic aneurysms in our study." (PMID 34834523, 2021).
arterial disease (2 papers, 2016 to 2022). "The association of the PCSK9 locus with VTE was unexpected, given that lipid accumulation and inflammation are generally considered less relevant to VTE than arterial disease." (PMID 35501368, 2022).
arteriosclerosis (2 papers, 2020 to 2026). A vascular disorder characterized by thickening and hardening of the walls of the arteries. "Compared with statins alone, the utilization of PCSK9 inhibitors demonstrated a marked improvement in the progression of arteriosclerosis, effectively reducing stenosis degree, plaque length, and volume." (PMID 41601579, 2026).
atopic dermatitis (2 papers, 2022 to 2024). "The development of atopic dermatitis while on PCSK9 inhibition was accompanied by a high serum IgE." (PMID 35862195, 2022).
breast invasive carcinoma (2 papers, 2024). "A pan-cancer analysis found that PCSK9 expression was considerably higher in invasive breast carcinoma." (PMID 38611089, 2024). "Other cancer types with heightened PCSK9 expression were head and neck squamous cell carcinoma (HNSC), uterine corpus endometrial carcinoma (UCEC), breast invasive carcinoma (BRCA), and thyroid carcinoma (THCA)." (PMID 38185721, 2024).
cardioembolic stroke (2 papers, 2023 to 2025). "The SMR revealed that expression of PCSK9 was associated with risk of AS (OR, 1.15; 95% CI, 1.03–1.28; p = 0.01), AIS (OR, 1.02; 95% CI, 1.14–1.29; p = 0.03), cardioembolic stroke (CES) (OR, 1.28; 95% CI, 1.01–1.61; p = 0.04)." (PMID 37528862, 2023).
cardiomyopathy (2 papers, 2023 to 2025). A disease of the heart muscle or myocardium proper. "PCSK9 deficiency is strongly linked to the development of cardiomyopathy, characterised by impaired mitochondrial oxidative capacity, altered substrate utilisation, and deteriorated contractile function." (PMID 41008547, 2025). "PCSK9, despite its low expression in cardiomyocytes, contributes to cardiac metabolic function, and PCSK9 deficiency in cardiomyocytes is linked to cardiomyopathy, impaired heart function, and compromised energy production." (PMID 36880401, 2023). "Mechanistically, therapeutic silencing of the mitochondrial cholesterol transporter TSPO in CM-Pcsk9−/− mice prevents cholesterol accumulation within mitochondria and restores cardiac performance, suggesting a metabolic rescue strategy in PCSK9-deficient cardiomyopathy." (PMID 41008547, 2025).
carotid artery thrombosis (2 papers, 2020 to 2021). Blood clot formation in any part of the carotid arteries. "The direct involvement of PCSK9 in platelet activation (PA) was confirmed by PCSK9-/- animal models of mice that presented reduced FeCl3 injury-induced carotid artery thrombosis." (PMID 32252393, 2020). "Additionally, several animal studies using PCSK9 over expressing or PCSK9 knockout mice model found that an interesting phenomenon related to PCSK9 and hypercoagulable state, platelet activation and carotid artery thrombosis." (PMID 34809656, 2021).
cerebral infarct (2 papers, 2024 to 2025). "Circulating PCSK9 concentrations were significantly higher in symptomatic patients or cases diagnosed with cerebral infarction (p < 0.01)." (PMID 38402551, 2024). "A recent animal experiment showed that PCSK9 inhibitor evolocumab improved neurobehavioral functions and reduced cerebral infarct volumes, which may be mediated by attenuating neuroinflammation through activation of the GPNMB/CD44 pathway." (PMID 41368357, 2025).
colorectal tumor (2 papers, 2022 to 2025). "Proprotein convertase subtilisin/kexin type 9 (PCSK9) has recently gained attention due to its overexpression in colorectal tumor tissues and its potential role in driving metastatic progression." (PMID 40563628, 2025). "In summary, PD-1 blockade showed a significant influence on the gene expression of lipid metabolism-related proteins including PCSK9 in colorectal tumors." (PMID 36003387, 2022).
diabetic cardiomyopathy (2 papers, 2025 to 2026). Diabetic cardiomyopathy is a disorder of the heart muscle in people with diabetes. "Our data demonstrate that the PCSK9 inhibitor alirocumab provides protective effects against diabetic cardiomyopathy, offering fundamental experimental support for its clinical application in this condition." (PMID 41828564, 2026). "This study aims to further validate whether PCSK9 inhibitors can improve diabetic cardiomyopathy and elucidate their mechanisms of action." (PMID 41828564, 2026).
familial hyperlipidemia (2 papers, 2021 to 2022). An instance of hyperlipidemia (disease) that is caused by an inherited modification of the individual's genome. "According to these findings, Pcsk9-related severe coronary artery lesions in PMI patients did not relate to familial hyperlipidemia and may be caused by the effects of Pcsk9 on LDL receptors, resulting in increased serum LDL-C levels." (PMID 34044829, 2021). "In Bulgaria, Borissov examines the effect of adding PCSK9 inhibitor treatment to statin treatment for patients with heterozygous familial hyperlipidemia (with or without existing CVD)." (PMID 35342693, 2022).
Fungal infections (2 papers, 2021 to 2024). "Fungal infections of 21 patients were not related to a change in PCSK9 (p = 0.226)." (PMID 39051245, 2024).
gram-negative bacterial infections (2 papers, 2019 to 2020). Infections caused by bacteria that show up as pink (negative) when treated by the gram-staining method. "For example, in the presence of Gram-negative bacterial infection, LPS could obviously upregulate the expression of PCSK9, while PCSK9 could further enhance the inflammatory reactions through modulating the TLR-4/NF-κB signaling pathway." (PMID 33123601, 2020).
head and neck squamous cell carcinoma (2 papers, 2024). A squamous cell carcinoma that arises from any of the following anatomic sites: lip and oral cavity, nasal cavity, paranasal sinuses, pharynx, larynx, and salivary glands. "A similar conclusion was reached in patients with head and neck squamous cell carcinoma, in whom a higher tissue protein PCSK9 expression indicated not only a poorer prognosis but also a stemness-like phenotype and a higher infiltration and activity of CD8+ T lymphocytes." (PMID 38611089, 2024).
hemorrhage (2 papers, 2022 to 2024). Loss of blood from the vascular compartment to the exterior or into nonvascular body space as a result of rupture or severance of the blood vessels. "A retrospective study indicated that PCSK9 inhibitors in AIS patients undergoing post-mechanical thrombectomy may lead to improved discharge outcomes and decrease the occurrence of hemorrhage and early neurologic deterioration." (PMID 39764289, 2024).
hepatitis B (2 papers, 2021 to 2022). "A separate study also described higher PCSK9 mRNA and protein in the fibrotic human liver obtained from patients with hepatitis B infection and patients with non-viral disease etiology." (PMID 33920491, 2021).
hepatitis C virus infection (2 papers, 2021 to 2025). A viral infection caused by the hepatitis C virus. "Hepatitis C virus infection causes hepatic and systemic inflammation, and effectively eliminating the virus lowers systemic inflammation and PCSK9 levels." (PMID 41271978, 2025).
hyperandrogenemia (2 papers, 2019 to 2025). "One of them evaluated the PCSK9 polymorphisms rs562556 with serum lipids level in Polycystic Ovary Syndrome subjects." (PMID 31036026, 2019).
hyperchylomicronemia (2 papers, 2018 to 2022). "Further studies of PCSK9 levels in patients with hyperchylomicronemia would be interesting in order to verify if all homozygous patients with T1HLP have low PCSK9 levels." (PMID 36061186, 2022).
hyperuricemia (2 papers, 2022 to 2024). An abnormally high level of uric acid. "Conversely, a positive relationship was observed between PCSK9 inhibition and hyperuricemia, while no genetic association with gout was detected." (PMID 39926389, 2024).
Hypoalbuminemia (2 papers, 2022 to 2025). The concentration of albumin in the blood circulation is below the lower limit of normal. "Hypoalbuminemia is associated both with elevated PCSK9 levels and all-cause mortality in the present study." (PMID 35354429, 2022).
juvenile absence epilepsy (2 papers, 2024 to 2026). A genetic epilepsy with onset occurring around puberty. "The risk of juvenile absence epilepsy (JAE) was also associated with higher expression of PCSK9 (OR = 1.06, 95% CI: 1.02 to 1.09, p = 0.002)." (PMID 38523609, 2024). "PCSK9 inhibition was linked to reduced risks of generalized epilepsy with tonic-clonic seizures (OR = 0.99; 95% CI: 0.98-1.00; P = 1.4 × 10-2), juvenile absence epilepsy (OR = 0.96; 95% CI: 0.93-1.00; P = 2.7 × 10-2), and juvenile myoclonic epilepsy (OR = 0.96; 95% CI: 0.93-1.00; P = 2.9 × 10-2)." (PMID 41861198, 2026).
kidney failure (2 papers, 2016 to 2022). An acute or chronic condition that is characterized by the inability of the kidneys to adequately filter the blood. "Alternatively, these high PCSK9 levels may also be due to the inflammatory nature of kidney failure often observed in maintenance HD patients." (PMID 35354429, 2022).
lung Injury (2 papers, 2022 to 2025). "An upcoming study may shed more light on the importance of PCSK9 and associated molecular pathways in patients at risk for acute lung injury: IMPACT-SIRIO 5 study (NCT04941105)." (PMID 35770004, 2022).
lung squamous cell carcinoma (2 papers, 2023 to 2024). "PCSK9 expression was significantly associated with immune infiltrate since specific markers of CD8+ T cells, macrophage polarization, and exhausted T cells exhibited different PCSK9-related immune infiltration patterns in LIHC and lung squamous cell carcinoma." (PMID 37860186, 2023).
memory impairment (2 papers, 2025 to 2026). "The OSLER-1 trial and ODYSSEY LONG TERM trial indicated that the incidence of memory loss was higher in patients treated with PCSK9 inhibitors compared to those receiving placebo." (PMID 40981245, 2025). "A total of 389 cases of memory loss associated with PCSK9 inhibitors have been reported, with memory impairment and amnesia being the most frequently documented adverse effects in the FAERS." (PMID 40981245, 2025).
migraine (2 papers, 2023 to 2024). "In contrast, ABCG5/ABCG8 enhancement, APOB inhibition, NPC1L1 inhibition, PCSK9 inhibition was found to be suggestively associated with higher risk of migraine." (PMID 37596566, 2023). "Interestingly, genetic variations in other lipid-lowering targets, such as APOB or PCSK9, which are associated with higher LDL cholesterol levels, have also been linked to a reduced risk of migraines." (PMID 39204161, 2024).
mixed hyperlipidemia (2 papers, 2022). "Not surprisingly, the effects of PCSK9 antibodies on triglyceride metabolism are more pronounced in patients with insulin-dependent type-2 diabetes and mixed hyperlipidemia, as shown in the ODYSSEY DM-INSULIN study." (PMID 35052871, 2022).
neuroblastoma (2 papers, 2023). Neuroblastoma (NB) is the most common solid, extracranial childhood tumor. "Finally, our observation that aberrant PCSK9 expression was associated with a poorer prognosis and immunity in neuroblastoma is consistent with previous pan-cancer findings." (PMID 37860186, 2023). "Plasmid carrying mini-RfxCas13d and each Pcsk9 crRNA were transfected into mouse neuroblastoma (N2a) cells that overexpressed a Pcsk9 mRNA fragment." (PMID 37684268, 2023). "Therefore, we further verified the expression changes of PCSK9 in neuroblastoma clinical samples as a supplemental study." (PMID 37860186, 2023). "Finally, we validated PCSK9 expression in clinical neuroblastoma samples and concluded that PCSK9 appeared to correlate with a poor PFS and natural killer cell infiltration in neuroblastoma patients." (PMID 37860186, 2023). "PCSK9 expression changes in neuroblastoma was not verified in the databases used in this study." (PMID 37860186, 2023).
neuroendocrine neoplasm (2 papers, 2021). Endocrine tumors, also referred to as neuroendocrine tumors (NETs), are defined by a common phenotype which is characterized by the expression of general markers (neuron specific enolase, chromogranin, synaptophysin) and hormone secretion products. "For example, miR-224 was identified as a potent inhibitor of PCSK9 expression in hepatocytes and subsequently found to regulate PCSK9 in human neuroendocrine tumors, where its overexpression restricted tumor cell proliferation and invasion." (PMID 34322524, 2021).
obstructive sleep apnea (2 papers, 2024 to 2025). "For instance, in patients with obstructive sleep apnea, which involves chronic intermittent hypoxia, PCSK9 levels were higher than in control subjects." (PMID 41446579, 2025).
peritonitis (2 papers, 2016 to 2019). Inflammation of the peritoneum (tissue that lines the abdominal wall and covers most of the organs in the abdomen). "Pharmacological inhibition of PCSK9 improves survival and inflammation in a murine polymicrobial peritonitis model, while Pcsk9 knockout mice display decreased production of inflammatory cytokines in response to LPS." (PMID 27171436, 2016).
preeclampsia (2 papers, 2023 to 2025). Preeclampsia is a hypertensive disorder of pregnancy that is characterized by new-onset hypertension with proteinuria presenting after 20 weeks of gestation, and depending on mild or severe forms may initially present with severe headache, visual disturbances, and hyperreflexia. "Receiver operating characteristic curve (ROC) analysis was performed to investigate whether the PCSK9 protein factor could be considered a diagnostic factor for preeclampsia." (PMID 38077944, 2023). "In preeclampsia, PCSK9 expression has also been reported to decrease relative to controls, most prominently in early-onset disease (PE vs. CTRL, median: 0.2 vs. 0.9, p = 0.010; PE vs. LP, median: 0.2 vs. 1.2, p = 0.012)." (PMID 41446579, 2025). "PCSK9 concentration in the preeclampsia group showed a significant increase (p < 0.001) compared to the control group." (PMID 38077944, 2023). "In general, the results of our study confirmed the role of PCSK9 and oxidative stress and its related indicators in preeclampsia." (PMID 38077944, 2023). "By investigating the serum concentration of PCSK9 factor in the patients with preeclampsia and comparing it with the control group, a significant increase in this factor was observed in the patient group compared to the control group." (PMID 38077944, 2023). "The analysis results below the ROC diagram in the PCSK9 factor for preeclampsia cases and control group were obtained as [0.913 (95% CI, 0.88-0.975)]." (PMID 38077944, 2023). "The concentrations of total cholesterol, low-density lipoprotein cholesterol (LDL-C), PCSK9, total antioxidant capacity, and malondialdehyde levels were higher in the preeclampsia group compared with control (p < 0.02)." (PMID 38077944, 2023). "The results of this study show a high level of PCSK9 and oxidative stress levels as well as its relationship with preeclampsia." (PMID 38077944, 2023). "In this study, we examined the levels of PCSK9 protein factor, as an indicator of oxidative stress, in women with preeclampsia." (PMID 38077944, 2023). "However, several independent studies report that placental PCSK9 expression is reduced in preeclampsia." (PMID 41446579, 2025). "This study aimed to evaluate the lipid profile, PCSK9 levels, and oxidative stress in preeclampsia." (PMID 38077944, 2023). "So, it may be said that PCSK9 protein can be involved in oxidative stress and was affected through certain pathways in the occurrence of preeclampsia." (PMID 38077944, 2023). "Also, the PCSK9 in the preeclampsia group had a significant negative association with SOD (p = 0.07, β = -0.596), GPx (p = 0.04, β = -0.015), GSH (p = 0.01, β = -0.426) and TAC (p = 0.04, β = -0.585)." (PMID 38077944, 2023). "Thus, the mechanisms controlling PCSK9 and SNX17 under hypoxia and preeclampsia remain insufficiently understood and may have practical relevance for preventing fetal lipid imbalance and developing new therapeutic strategies in preeclampsia." (PMID 41446579, 2025). "Therefore, we aimed to investigate the relationship between lipid profile (triglyceride, cholesterol, HDL-C and LDL-C), PCSK9 concentration, and oxidative stress markers such as SOD, GPx, malondialdehyde, glutathione, total antioxidant capacity, and total oxidant status levels in preeclampsia women." (PMID 38077944, 2023).